DYNC1I1 (dynein cytoplasmic 1 intermediate chain 1)
Diseases named in the same sentence as DYNC1I1 in open-access papers (continued):
Sharing a sentence is not in itself a finding about the gene and the disease.
rectal adenocarcinoma (1 paper, 2024).
tumor (8 papers, 2019 to 2025). "Amplifications in the ALK, DYNC1I1, and TRRAP genes were found in one tumor, which also showed a point mutation in TERT (each 5%)." (PMID 40227833, 2025). "In contrast, the high expression of DYNC1I1, FAM83D, and LBH, have been previously associated with poor prognosis and an aggressive tumor phenotype in GC." (PMID 37772256, 2023). "The results of UALCAN analysis showed that DYNC1I1 overexpression was positively correlated with cancer stage, tumor grade, nodal metastasis status, and histological subtypes of HCC." (PMID 35002514, 2022). "Consistent with this, re-expression of DYNC1I1 in the tumor cells reduced the plasma membrane localization of SK2, and reduced U251 GBM tumor growth in mice." (PMID 31906280, 2020). "Together, our findings indicate a novel tumor-suppressive function of DYNC1I1 in GBM via dynein-mediated regulation of SK2." (PMID 30250299, 2019). "At the same time, to determine differences of DYNC1I1 mRNA expression in tumor and normal tissues, the DYNC1I1 mRNA levels in GC tumors and normal tissues were analyzed using the Oncomine database." (PMID 31249807, 2019). "Re-expression of DYNC1I1 reduced plasma membrane-localized SK2 and extracellular S1P formation, and decreased GBM tumor growth and tumor-associated angiogenesis in vivo." (PMID 30250299, 2019). "For person neoplasm cancer status, LOC285000 and LEP could distinguish the prognosis of patients free from neoplasm, while SLC30A3 and DYNC1I1 were significant for patients with neoplasm." (PMID 32528533, 2020). "Notably, re-expression of DYNC1I1 in GBM cells reduced plasma membrane-localized SK2 and extracellular S1P formation and, strikingly, decreased tumor growth and tumor-associated angiogenesis in vivo." (PMID 30250299, 2019).
cancer (7 papers, 2019 to 2024). A tumor composed of atypical neoplastic, often pleomorphic cells that invade other tissues. "The intermediate chain, DYNC1I1, has rarely been associated with tumors and its role in cancer remains controversial." (PMID 31249807, 2019). "KLC1 was significantly reduced in both cancer cell lines, while DYNC1I1 had notably higher protein amounts in PC-3 compared to LNCaP cells." (PMID 39217195, 2024). "In addition, some studies have reported that the upregulation of DYNC1I1 could inhibit the apoptosis of cancer cells and promote the proliferation and migration of cancer cells." (PMID 35002514, 2022). "Notably, the knockdown of DYNC1I1 had a universal inhibitory effect on migration in both non-malignant PNT1a cells (P ≤ 0.01) and PC-3 (P ≤ 0.01) cancer cells." (PMID 39217195, 2024). "Furthermore, by screening through the criteria of the PPI network, cancer-related pathway and TRS modeling, essential features with gene symbols of EPB41, PSMA1, FGFR3, MRAS, LEP, C7orf46, LOC285000, LBP, ZNF35, SLC30A3, LECT2, RNF7, and DYNC1I1 were identified as PRBs for COAD patients." (PMID 32528533, 2020).
DYNC1I1 also shares sentences with these, for which no sentence is quoted: colon cancer (2 papers); amyotrophic lateral sclerosis (1); Brugada syndrome (1); Cornelia de Lange syndrome (1); diabetes (1); Ectrodactyly (1); Hyperglycemia (1); inguinal herniae (1); Intellectual disability (1); Joubert syndrome 31 (1); mitral valve prolapse (1); musculoskeletal disorder (1); personality disorder (1); prostate adenocarcinoma (1); prostate tumors (1); sensorineural hearing loss (1); short-rib thoracic dysplasia (1); systemic lupus erythematosus (1); Urbach-Wiethe disease (1).